DMD (dystrophin)
Diseases named in the same sentence as DMD in open-access papers (continued):
Sharing a sentence is not in itself a finding about the gene and the disease.
Duchenne muscular dystrophy (continued). "Mutations in dystrophin cause Duchenne muscular dystrophy, and dystrophin loss in cachectic muscles leads to DGC dissociation, and correlates with induction of UPS components, and atrophy." (PMID 33467597, 2021). "Duchenne muscular dystrophy (DMD) is a progressive muscular degeneration disease caused by the complete loss of dystrophin protein, eventually leading to ambulatory and respiratory deficiency, whose symptoms typically occur in early childhood." (PMID 34829817, 2021). "We have previously published validation of the OGM technology to identify variants in the DMD gene in a cohort of patients with Duchenne muscular dystrophy." (PMID 33407088, 2021). "A leading example is Duchenne muscular dystrophy, resulting from loss of dystrophin, which has been studied extensively with important translational insights." (PMID 34805146, 2021). "This pathological mechanism suggests that DGpathy patients exhibit muscle pathology similar to those of patients with dystrophin-deficient Duchenne-type muscular dystrophy (DMD)." (PMID 34884967, 2021). "Viltolarsen is an antisense oligonucleotide approved for the treatment of Duchenne muscular dystrophy (DMD) in patients with a specific DMD gene mutation." (PMID 33864098, 2021). "DG was first identified as a glycoprotein that interacts with dystrophin, the causative gene product of Duchenne muscular dystrophy, in skeletal muscle." (PMID 34884967, 2021). "Duchenne muscular dystrophy (DMD) gene encodes for the protein dystrophin and its mutation has also been pointed out in meningiomas." (PMID 34679551, 2021). "Duchenne muscular dystrophy (DMD) is a severe X-linked myodegenerative disease caused by defective expression of full-length dystrophin, a cortical cytoskeletal protein with a molecular mass of 427 kDa (Dp427)." (PMID 32982660, 2020). "Duchenne muscular dystrophy is a severe muscle wasting disease caused by mutations in the dystrophin gene (dmd)." (PMID 32343037, 2020). "Duchenne muscular dystrophy (DMD) is a fatal muscle‐wasting disorder caused by genetic loss of dystrophin protein." (PMID 31849191, 2020). "Duchenne muscular dystrophy is caused by mutations in the gene that encodes dystrophin, a protein that forms part of dystrophin glycoprotein complex, which connects the sarcolemma to the extracellular matrix, conferring membrane stability." (PMID 32560255, 2020). "Duchenne muscular dystrophy (DMD) is caused by a nonsense or frameshift mutation in the DMD gene, while its milder form, Becker muscular dystrophy (BMD) is caused by an in-frame deletion/duplication or a missense mutation." (PMID 31919629, 2020). "Duchenne muscular dystrophy (DMD) is a devastating muscle disease caused by mutations of the DMD gene, which encodes dystrophin." (PMID 32313117, 2020). "ECC protocols distinguish dystrophin-deficient from healthy, wild type muscle, and test the efficacy of therapeutics for Duchenne muscular dystrophy (DMD)." (PMID 32007101, 2020). "Duchenne Muscular Dystrophy (DMD) is caused by mutations of the dystrophin gene and is the most common of the muscular dystrophies." (PMID 33361519, 2020). "For example, the genetic analysis and positional cloning revealed a dystrophin gene mutation responsible for the Duchenne muscular dystrophy in 1987." (PMID 32825241, 2020). "Muscle stem cell dysfunction is one of the contributing factors in Duchenne muscular dystrophy, a severely debilitating muscle degenerative disease that results from the genetic loss of the dystrophin gene Dmd." (PMID 32195258, 2020). "An example, approved by the Food and Drug Administration, is Eteplirsen, a drug used to treat Duchenne muscular dystrophy caused by loss-of-function mutations in the DMD gene coding for dystrophin." (PMID 32754048, 2020). "Duchenne muscular dystrophy (DMD) is caused by frameshift mutations in the DMD gene that prevent the body-wide translation of its protein product, dystrophin." (PMID 31836945, 2020).
Duchenne muscular dystrophy (continued). "Duchenne muscular dystrophy is a severe muscle wasting disease in which a host of cellular pathways are altered secondary to a dystrophin protein deficiency." (PMID 32109352, 2020). "Duchenne muscular dystrophy (DMD) is a genetic disease caused by mutations of a gene located in the X chromosome that codifies for dystrophin, a protein that connects the cytoskeleton with the sarcolemma, stabilizing the cell membrane." (PMID 32751416, 2020). "Duchenne muscular dystrophy (DMD) is progressive muscle wasting X-linked recessive genetic disorder caused by out of frame mutations in the dystrophin gene resulting in severe cellular and molecular changes." (PMID 33330096, 2020). "Duchenne muscular dystrophy (DMD) is a lethal X-linked muscular disease caused by defective expression of the cytoskeletal protein dystrophin (Dp427)." (PMID 32982660, 2020). "Duchenne muscular dystrophy (DMD) is an X-linked inherited neuromuscular disorder caused by mutations in the dystrophin gene." (PMID 32153426, 2020). "For instance, HC-AdV-mediated delivery of high-specificity RGN pairs targeting a mutational hotspot in the dystrophin-encoding DMD gene, whose mutations underlie Duchenne muscular dystrophy, permitted restoring the DMD reading frame in muscle progenitor cells." (PMID 32973430, 2020). "This has been reflected in a study that utilised the Cas12a nuclease to correct mutations in the dystrophin gene (DMD) that causes Duchenne muscular dystrophy (DMD)." (PMID 32198625, 2020). "The pathology of this disease is generally milder than that of Duchenne muscular dystrophy, known as a more severe form of X-linked muscular dystrophy caused by the complete loss of the dystrophin protein." (PMID 32859695, 2020). "The neuromuscular disorder Duchenne muscular dystrophy is due to primary abnormalities in the DMD gene, which encodes several different isoforms of the protein dystrophin." (PMID 32916630, 2020). "Duchenne muscular dystrophy (DMD) is an incurable X-linked recessive disorder characterized by mutations in the dystrophin gene." (PMID 32231219, 2020). "Duchenne muscular dystrophy (DMD) is an X-linked inherited disorder due to mutations in the Dystrophin gene." (PMID 32767978, 2020). "In conclusion, the outcomes of this study contribute to the further understanding of BMD pathology and help elucidate the efficiency of dystrophin recovery treatments in Duchenne muscular dystrophy, a more severe form of X-linked muscular dystrophy." (PMID 32859695, 2020). "Duchenne muscular dystrophy is primarily characterized by progressive muscle wasting due to deficiency in the membrane cytoskeletal protein dystrophin but is also associated with body-wide cellular disturbances in a variety of non-muscle tissues." (PMID 32916630, 2020). "Duchenne muscular dystrophy (DMD) is a fatal X-linked recessive neuromuscular disorder most commonly caused by mutations disrupting the reading frame of the dystrophin (DMD) gene." (PMID 32213923, 2020). "In our previous study, the dystrophin deficient (Duchenne muscular dystrophy) rats exhibited muscle tissue pathology similar to that of muscular dystrophy, exhibiting continuous muscle degeneration and deposition of intramuscular fibrous tissues and fat." (PMID 32859695, 2020). "Duchenne muscular dystrophy (DMD) is a genetic disorder that causes alterations in dystrophin leading to muscle degeneration and frailty." (PMID 32897420, 2020). "Duchenne muscular dystrophy (DMD) is a fatal X-linked recessive condition caused primarily by out-of-frame mutations in the dystrophin gene." (PMID 32650403, 2020). "Duchenne muscular dystrophy (DMD) is a severe muscle wasting disease typically caused by protein-truncating mutations that preclude synthesis of a functional dystrophin." (PMID 32630425, 2020).
Duchenne muscular dystrophy (continued). "Duchenne Muscular Dystrophy (DMD) is a severe muscle-wasting disease caused by mutations in the DMD gene encoding dystrophin, expressed mainly in muscles but also in other tissues like retina and brain." (PMID 32160266, 2020). "Mutations in the dystrophin gene in Duchenne muscular dystrophy (DMD) and Becker muscular dystrophy (BMD), or sarcoglycan genes in limb-girdle muscular dystrophies (LGMDs) lead to muscle sarcolemma destabilization and fragility." (PMID 33240103, 2020). "Duchenne muscular dystrophy (DMD) is a genetic disorder caused by loss of the protein dystrophin, characterized by severe muscle wasting." (PMID 32483463, 2020). "Loss of dystrophin in Duchenne muscular dystrophy (DMD) leads to muscle degeneration and regeneration, and impairs the contractile function of muscles." (PMID 32000855, 2020). "Duchenne muscular dystrophy (DMD) is a form of muscular dystrophy associated with X-linked recessive disorder caused by mutation of dystrophin in SM." (PMID 32722232, 2020). "Duchenne muscular dystrophy (DMD) is a degenerative muscle disease caused by mutations in the dystrophin gene." (PMID 32948250, 2020). "Duchenne muscular dystrophy (DMD) is an invariably fatal neuromuscular X-linked recessive disorder caused by mutations in the dystrophin gene, affecting 250,000 people worldwide and one in every 5,000 male infants." (PMID 32219101, 2020). "Ataluren promotes ribosomal read‐through of a premature termination codon in the dystrophin mRNA, a cause of Duchenne muscular dystrophy, resulting in production of full‐length protein." (PMID 32196986, 2020). "Dystrophin Dp71 is the smallest isoform of the DMD gene, mutations in which cause Duchenne muscular dystrophy (DMD)." (PMID 33051488, 2020). "Duchenne muscular dystrophy (DMD) is an X‐linked genetic muscle disorder that results from the presence of mutations in the gene that encodes the dystrophin protein." (PMID 32196986, 2020). "Duchenne muscular dystrophy (DMD) is an X-linked disorder caused by the lack of functional dystrophin protein." (PMID 33101056, 2020). "Golodirsen (Vyondys 53TM) is used for the treatment of Duchenne muscular dystrophy (DMD) with genetic mutations subject to skipping exon 53 of the dystrophin gene." (PMID 32050446, 2020). "There are two types of MD associated with DMD mutations: Duchenne’s muscular dystrophy (DMD) and Becker’s muscular dystrophy (BMD)." (PMID 32977524, 2020). "Duchenne muscular dystrophy (DMD) is a progressive muscle-wasting disease caused by mutation of the dystrophin gene." (PMID 32718931, 2020). "In Duchenne muscular dystrophy, mutations in the X-linked gene dystrophin leads to progressive weakness in striated muscles." (PMID 33002037, 2020). "Duchenne muscular dystrophy (DMD) is a fatal neuromuscular disease caused by deleterious mutations in the DMD gene which encodes the dystrophin protein." (PMID 32488044, 2020). "The DMD gene is one of the largest human genes, being composed of 79 exons, and encodes dystrophin Dp427m which is deficient in Duchenne muscular dystrophy (DMD)." (PMID 32443516, 2020). "Duchenne muscular dystrophy (DMD) is an X-linked muscle wasting disease that is caused by the loss of functional dystrophin protein in cardiac and skeletal muscles." (PMID 31628052, 2020). "Dystrophinopathies are X-linked diseases, including Duchenne muscular dystrophy and Becker muscular dystrophy, due to DMD gene variants." (PMID 32424326, 2020). "Deletions, duplications, rearrangements, and point mutations in DMD, the dystrophin gene, have been strongly linked to Duchenne muscular dystrophy (DMD), Becker muscular dystrophy (BMD), and cardiomyopathy." (PMID 31388106, 2019). "Duchenne muscular dystrophy is an X-linked disease caused by a mutation in the DMD gene that encodes dystrophin protein." (PMID 31824418, 2019).
Duchenne muscular dystrophy (continued). "In dystrophin-deficient mice, a model of Duchenne muscular dystrophy (DMD) which develops fibrosis and DCM, an altered profibrotic gene expression profile, in particular, a steep increase in Lox mRNA expression has been documented)." (PMID 31766500, 2019). "The protein encoded by this transcript is called dystrophin since mutations lead to the Becker and Duchenne muscular dystrophies." (PMID 31266185, 2019). "The role of DMD as a tumor suppressor in sarcomas is strengthened by the observation that dystrophin-deficient mdx mice, which are murine models for Duchenne muscular dystrophy, spontaneously develop rhabdomyosarcomas in 6–9% of cases." (PMID 31266185, 2019). "Duchenne muscular dystrophy is caused by loss-of-function mutations, most commonly deletions, within the DMD gene." (PMID 31645977, 2019). "Duchenne muscular dystrophy (DMD) is an X-linked recessive genetic disease in which the dystrophin coding for a membrane stabilizing protein is mutated." (PMID 31877123, 2019). "Duchenne muscular dystrophy (DMD) is a fatal genetic disorder caused by mutations in the dystrophin gene." (PMID 31586095, 2019). "We find that genetic dystrophin loss provides a second hit for MR-mediated cardiomyopathy in Duchenne muscular dystrophy model mice, as aldosterone worsens fibrosis, mass and dysfunction phenotypes." (PMID 30745312, 2019). "Duchenne muscular dystrophy (DMD) is an X-linked disorder due to mutations in the DMD dystrophin gene and presents in early childhood with proximal muscle weakness." (PMID 31027200, 2019). "Skeletal muscle weakness is a major feature of Duchenne muscular dystrophy (DMD) due to a deficiency in the protein dystrophin." (PMID 31771272, 2019). "For example, in the X-linked recessive disorder Duchenne muscular Dystrophy (DMD), a number of female cases with translocations that forced the inactivation of the normal DMD allele, were already reported in the 1980s." (PMID 30552425, 2019). "Cognitive deficit has been identified in one third of patients affected by Duchenne Muscular Dystrophy, primarily attributed to loss of the short Dp71 dystrophin, the major brain dystrophin isoform." (PMID 30646960, 2019). "Dystrophin-deficient mice are used to test corrective strategies for Duchenne muscular dystrophy, but evaluation of dystrophin expression requires collection of tissue samples from specific muscles and time points." (PMID 31586095, 2019). "This protein is found to interact directly with dystrophin and the low expression level of it will cause severe Duchenne muscular dystrophy." (PMID 31105557, 2019). "Duchenne Muscular Dystrophy (DMD) is an X-linked neuromuscular disorder caused by a mutation in the dystrophin gene." (PMID 31612351, 2019). "The SNTG1 gene is a cytoplasmic membrane protein that associates with the Duchenne muscular dystrophy gene, dystrophin." (PMID 31506096, 2019). "Dystrophin Dp71 is one of the most widely expressed isoforms of dystrophin, the pathogenic gene of Duchenne muscular dystrophy (DMD), an X-linked recessive disorder." (PMID 31236120, 2019). "In Duchenne muscular dystrophy, loss or truncated forms of dystrophin leave the membrane highly susceptible to contraction-induced injury and hypoxic stress, which has deleterious consequences for the intra-myofibrillar environment." (PMID 30764835, 2019). "Duchenne Muscular Dystrophy (DMD) is one of the most severe dystrophies caused by mutations that lead to the loss of a functional dystrophin protein, a structural protein associated to the muscle fiber membrane." (PMID 31626629, 2019). "For example, it can restore dystrophin protein expression in cardiac and skeletal muscle by correcting mutations responsible for Duchenne muscular dystrophy (DMD)." (PMID 31124015, 2019). "Duchenne Muscular Dystrophy (DMD) is a progressive lethal disease caused by X-linked mutations of the dystrophin gene." (PMID 31612351, 2019).
Duchenne muscular dystrophy (continued). "Duchenne muscular dystrophy (DMD) is an X-linked genetic disorder resulting from a mutation of the dystrophin gene that leads to severe muscle degeneration as well as fibrosis of connective tissue." (PMID 31108916, 2019). "Duchenne muscular dystrophy (DMD) is caused by loss of dystrophin protein, leading to progressive muscle weakness and premature death due to respiratory and/or cardiac complications." (PMID 30281092, 2019). "Individuals with Duchenne muscular dystrophy (Duchenne) lack functional dystrophin protein expression due to pathogenic variants in the DMD (OMIM 300377) gene located on the X‐chromosome (Xp21)." (PMID 30450799, 2019). "Duchenne muscular dystrophy (DMD) is an X-linked recessive defect caused by dystrophin gene mutation." (PMID 30934785, 2019). "Duchenne muscular dystrophy is a severe, progressive muscle-wasting disease that is caused by mutations that abolish the production of functional dystrophin protein." (PMID 30672725, 2019). "Duchenne muscular dystrophy is an inherited neuromuscular disease arising from loss-of-function mutations in the DMD gene." (PMID 31645977, 2019). "The approach that induces exon skipping to restore reading frame was developed for Duchenne muscular dystrophy patients with frameshift mutations in the DMD gene." (PMID 29680930, 2018). "Duchenne muscular dystrophy (DMD) is an inherited myogenic disorder due to mutations in the dystrophin gene on chromosome Xp21.1." (PMID 29304097, 2018). "IAV infection significantly increases muscle degeneration and decreases survival in the zebrafish model of Duchenne Muscular Dystrophy (dystrophin-deficient sapje mutant zebrafish)." (PMID 29615556, 2018). "Loss and/or diminished expression of dystrophin or DAPC components leads to a variety of muscular dystrophies such as Duchenne muscular dystrophy (DMD), Becker muscular dystrophy (BMD), and several forms of recessive limb-girdle muscular dystrophies (LGMD)." (PMID 30466494, 2018). "Duchenne muscular dystrophy (DMD), a fatal X-linked recessive disorder, is caused mostly by frame-disrupting, out-of-frame deletions in the dystrophin (DMD) gene." (PMID 30544634, 2018). "Duchenne muscular dystrophy (DMD) is a fatal neuromuscular disorder caused by mutations in the dystrophin gene." (PMID 29242210, 2018). "Duchenne muscular dystrophy (DMD), which involves a progressive deterioration of muscle function, is caused by frame-shifting deletions or nonsense mutations in the DMD gene resulting in the absence or reduced production of the dystrophin protein." (PMID 30400273, 2018). "Duchenne Muscular Dystrophy is a genetic disease that is caused by a deficiency of dystrophin protein." (PMID 29862132, 2018). "DYS-1 is the homolog of dystrophin in mammals and mutations in this gene cause Duchenne Muscular Dystrophy in Human41." (PMID 29743663, 2018). "Duchenne muscular dystrophy is caused by the mutation of the dystrophin-encoding gene that is responsible for maintaining muscle integrity." (PMID 30213032, 2018). "Duchenne muscular dystrophy (DMD) is a severe neuromuscular disorder occurring in 1 in 3500–5000 male births worldwide that is due to recessive mutations of the DMD gene on the X chromosome." (PMID 30477208, 2018). "The proteomic profiling of the mdx-4cv mouse model of Duchenne muscular dystrophy, which is characterized by a low frequency of revertant fibres, has established considerable changes in the dystrophin-deficient skeletal musculature, heart, brain and serum." (PMID 30386187, 2018). "Two known syndromes caused by the mutation of the dystrophin gene are Duchenne muscular dystrophy (DMD) and Becker muscular dystrophy (BMD)." (PMID 29998127, 2018). "Duchenne muscular dystrophy (DMD) is an X-linked muscle-wasting disease caused by mutations in the dystrophin gene." (PMID 30417024, 2018). "Duchenne muscular dystrophy (DMD) is a severe degenerative disorder caused by mutations in the dystrophin gene." (PMID 30194302, 2018).